KRAS (KRas proto-oncogene, GTPase)
Diseases named in the same sentence as KRAS in open-access papers (continued):
Sharing a sentence is not in itself a finding about the gene and the disease.
lung adenocarcinoma (continued). "Our results demonstrated a slightly higher incidence of KRAS mutations in lung adenocarcinomas than was previously reported for a Caucasian population, which might be due to the smoking habits of this Croatian population." (PMID 27655296, 2016). "Furthermore, higher levels of OTUB1 expression are observed specifically in lung adenocarcinomas harboring wt KRAS compared to mutated RAS tumors." (PMID 26881969, 2016). "According to a recent meta-analysis of 94 studies, the rate of EGFR mutation in lung adenocarcinoma in Asians (47.9%) is higher than that in Westerners (19.2%), while KRAS (11.2%) and LKB1 (4.0%) mutation rates are lower in Asians than in Westerners (26.1% and 16.2%, respectively)." (PMID 25760072, 2015). "In contrast to previous reports, our results indicate that the KIF5B-RET fusion gene may coincide with EGFR or KRAS mutations, albeit at a lower frequency, in lung adenocarcinomas." (PMID 26268359, 2015). "Nevertheless, it is important to address that the greatest prevalence of KRAS mutation in women has been previously observed in other cancer types such as in patients with lung adenocarcinoma, leading to the hypothesis of possible hormonal influence." (PMID 24720724, 2014). "Furthermore, let-7 can regulate several oncogenic pathways; for example, this miRNA negatively modulates multiple cell-cycle oncogenes as KRAS, mutation of which are commonly implicated in lung adenocarcinomas MYC and HMGA2." (PMID 25309923, 2014). "In addition, it was shown that OS in the KRAS mutation group was significantly poorer than those in the EGFR mutation or in both wild groups with completely resected lung adenocarcinoma." (PMID 23724098, 2013). "Therefore, KRAS mutations have been suggested to constitute a primary mechanism of resistance to gefitinib or erlotinib in lung adenocarcinoma." (PMID 23817662, 2013). "Therefore, a stepwise approach to test for gene mutations in lung adenocarcinoma is suggested: first for KRAS, second for EGFR, and then EML4-ALK translocation." (PMID 23341890, 2013). "DNA sequencing confirmed the presence of KRAS mutations, one of the most common driver mutations in lung adenocarcinoma, in three of the xenograft models and mutations in BRAF and NRAS, two less frequently occurring mutations associated with NSCLC, in two of the models." (PMID 22992329, 2012). "Ideally, the use of KRAS mutational analysis would be most helpful if the mutation was mutually exclusive to the lung adenocarcinoma, but there also exists a possibility that the patient may develop two distinct primaries that harbor identical KRAS mutations." (PMID 23119210, 2012). "However, the mutations in either gene in lung adenocarcinomas are rarely seen although the biological consequences of KRAS and EGFR mutations share similarities in regulation of cell proliferation, survival and apoptosis." (PMID 22174919, 2011). "The proto-oncogene KRAS is often mutated and is responsible for 10–30% of lung adenocarcinomas." (PMID 21532835, 2010). "The KRAS expression signature, developed from a mouse tumor model, was shown to be significantly enriched in KRAS mutated human lung adenocarcinoma data sets by a rank order-based statistical test to detect subtle but significant similarity hidden in genome-scale profiles." (PMID 19517027, 2008). "The prevalence of KRAS mutations in our cohort of lung adenocarcinomas was 12% (20/173)." (PMID 17487277, 2007).
lung adenocarcinoma (continued). "Notably, the comparable frequency of KRAS G12C mutations in the “large cell carcinoma” histology group and lung adenocarcinoma supports the hypothesis that a substantial portion of large cell carcinomas are undifferentiated TTF1-negative adenocarcinomas." (PMID 40075878, 2025). "Interestingly, Best and colleagues showed that murine models of lung adenocarcinoma harboring KRAS and LKB1 mutations exhibit increased glutaminase expression by tumor cells and increased glutamate in the tumor microenvironment, compared to KRAS mutant/KEAP1 mutant lung adenocarcinomas." (PMID 40255421, 2025). "Thus, it will be important to examine whether ERK3 S189 phosphorylation is increased in lung adenocarcinomas (LUADs) with KRAS G12 mutations versus LUADs expressing wild-type KRAS." (PMID 38611058, 2024). "Notably, KRAS-G12C mutations take up to 40% of all KRAS mutant lung adenocarcinoma cases." (PMID 38278976, 2024). "In addition, about 25–30% of lung adenocarcinoma patients obtain KRAS mutations." (PMID 37834062, 2023). "As such, we sought to interrogate the consequences of Setd2 inactivation in KRAS-driven lung adenocarcinoma in order to better understand how SETD2 deficiency drives early and widespread tumor growth and identify intrinsic therapeutic vulnerabilities that may exist." (PMID 36899051, 2023). "Therefore, this study aimed to explore whether the AMG-510 and cisplatin combination increases the antitumor effect in lung adenocarcinoma with the mutation of KRAS G12C by experiments in vitro and in vivo." (PMID 37284902, 2023). "However, for the 12 trials enrolling patients with non-specified NSCLC histology but with mandatory presence of EGFR mutations (n = 6), ALK rearrangements (n = 5), or KRAS mutations (n = 1), the vast majority of enrolled patients (> 90% for each study) had a diagnosis of lung adenocarcinoma." (PMID 37400832, 2023). "However, co-mutations may alter such efficacy, such as KRAS-mutant patients with STK11 or KEAP1, as co-mutations have a poorer prognosis for immunotherapy than KRAS wild-type lung adenocarcinoma patients." (PMID 36675641, 2023). "Therefore, targeting the metabolic vulnerabilities of LKB1 mutated cancer cells may reverse the resistance of PD-1 blockade therapy in lung adenocarcinoma patients with KRAS/LKB1 mutation." (PMID 36074553, 2022). "Besides, FKBP10 upregulation has been observed in KRAS mutation-induced lung adenocarcinoma, colorectal cancer renal cell carcinoma, gastric cancer and knockdown of FKBP10 expression could reverse the malignant phenotype, especially proliferation ability." (PMID 33557829, 2021). "Therefore, it can be speculated that the most common smoking‐related mutation in lung adenocarcinoma, KRAS, can be used as an effective predictor of anti‐PD‐1/PD‐L1 immunotherapy." (PMID 32342665, 2020). "Furthermore, in addition to the clinical and pathologic characteristics investigated in our study, other factors such as smoking status, EGFR mutation status, KRAS mutation status may also affect the survival of patients with lung adenocarcinoma." (PMID 32207885, 2020). "A case report of three patients with lung adenocarcinoma who developed pseudoprogression after anti‐PD‐1 therapy showed similar results in that when compared with the increase in patients with true progression, the level of KRAS‐mutated ctDNA was dramatically reduced to an undetectable level." (PMID 32997401, 2020).
lung adenocarcinoma (continued). "Therefore, the present study aims to investigate the frequency of EGFR and KRAS mutations in a large Brazilian series of lung adenocarcinoma, and to correlate the presence of these mutations with patients’ genetic ancestry and clinicopathological and sociodemographic characteristics." (PMID 30824880, 2019). "Importantly, this hypothesis is consistent with findings in gene expression studies performed on specific clinicopathological (smoking) or mutation subgroups (EGFR/KRAS) in lung adenocarcinoma." (PMID 27437773, 2016). "In lung adenocarcinoma, oncogenic KRAS mutations are highly prevalent (~25 %) but therapy choices are very limited suggesting that our findings might be of relevance to advance treatment of a significant fraction of lung adenocarcinoma patients." (PMID 27594806, 2016). "However, in the present study, no gender differences were observed in the characteristics of the EGFR- or KRAS-mutated lung adenocarcinomas other than tumor size, indicating that smoking status has a greater effect on the cause of lung adenocarcinoma than gender differences in Japanese patients." (PMID 24179496, 2013). "In addition to EGFR mutations and ALK rearrangements, genomic studies have also identified frequent copy number changes and somatic mutations affecting components of key signaling pathways in adenocarcinoma of the lung including KRAS, Her2, BRAF, C-MET, MEK1 and PIK3CA." (PMID 25562798, 2012). "E2A is overexpressed in lung adenocarcinoma and is significantly elevated in tumors harboring mutant KRAS." (PMID 41841523, 2026). "In this analysis, we selected three cancer types with high prevalence of KRAS somatic mutations: colon adenocarcinoma (COAD), pancreatic adenocarcinoma (PAAD), and lung adenocarcinoma (LUAD)." (PMID 41368203, 2026). "KRAS-driven lung adenocarcinoma treated with KRAS inhibitors initially exhibit features of alveolar type 2 (AT2) cells but upon treatment withstand therapy by acquiring features of alveolar type 1 (AT1) cells." (PMID 42001483, 2026). "Here we show that ageing reprograms the evolutionary trajectory of KRAS-driven lung adenocarcinoma, limiting primary tumour growth while promoting metastatic dissemination through epigenetic activation of the integrated stress response (ISR)." (PMID 41813904, 2026). "KRAS is one of the most frequently mutated oncogenes in lung adenocarcinoma (LUAD), with the KRAS-Q61H mutation representing a rare but biologically distinct subgroup." (PMID 41756324, 2026). "A vaccine targeting multiple epitopes of the KRAS molecule in a mouse model of a KRAS-driven lung tumor elicited Th1 immune response and reduced tumor burden and tumor number by > 80% in a genetically engineered mouse model for KRAS driven lung adenocarcinoma." (PMID 40437549, 2025). "More importantly, inhibition of GATA2 markedly inhibits the growth of KRAS-driven lung adenocarcinoma." (PMID 40647501, 2025). "It has been recently reported in lung adenocarcinoma patients and a tumor cell injection model that activated KRAS signaling triggers CD47 expression on tumor cells inhibiting their phagocytotic elimination." (PMID 40360735, 2025).
lung adenocarcinoma (continued). "Genetic alterations in key oncogenes have been frequently identified in lung adenocarcinoma (LUAD), including genes encoding epidermal growth factor receptor (EGFR), Kirsten rat sarcoma viral oncogene homolog (KRAS), and anaplastic lymphoma kinase (ALK)." (PMID 40621945, 2025). "In the second cohort, we performed IHC analysis of CD47 and RASON expression on an in-house-generated tissue microarray containing paired tumor and adjacent normal tissue samples from nine patients with KRAS-mutant lung adenocarcinoma." (PMID 40128846, 2025). "Ld1 reduces the resistance of lung adenocarcinoma cells to trametinib by regulating the KRAS pathway." (PMID 41003841, 2025). "In a series of lung adenocarcinoma patients metastatic to the spine with mutational data for selected markers (ALK, MET, ROS1, EGFR, and KRAS), the presence of clinically targetable mutations was found to be associated with increased survival." (PMID 40647516, 2025). "A recent study revealed that USP13 interacts with and catalyzes the deubiquitination of the transcription factor NFE2L2 and promotes an autophagy-to-ferroptosis switch in KRAS mutant lung adenocarcinoma." (PMID 41330897, 2025). "In lung adenocarcinoma, patients with obesity showed a lower prevalence of EGFR and a higher prevalence of KRAS mutations." (PMID 40149286, 2025). "Kirsten rat sarcoma (KRAS), the most commonly mutated oncogene in NSCLC, has a prevalence of 29% in lung adenocarcinoma." (PMID 40231258, 2025). "Clinically, combining eliglustat, a glycosphingolipids inhibitor, with checkpoint blockade therapies such as anti-CTAL4 or anti-PD-1, has been shown to suppress KRAS-driven lung adenocarcinoma (LUAD)." (PMID 39806421, 2025). "Prominent progress has been made in the identification and therapeutic targeting of unique genetic or molecular alterations of lung adenocarcinomas, including activating mutations in oncogenes such as EGFR and KRAS mutations." (PMID 40486486, 2025). "Approximately 8% of lung adenocarcinomas have concomitant STK11 loss and KRAS mutation, which confers a particularly poor prognosis." (PMID 40069402, 2025). "KRT8high alveolar intermediate cells are important intermediate state cells in the development of lung adenocarcinoma (LUAD) and are closely associated with KRAS mutations and tumor formation." (PMID 39354287, 2025). "In non-small cell lung cancer (NSCLC), KRAS G12C represents the most prevalent KRAS mutation subtype, accounting for approximately 11–16% of all NSCLC cases and 13% of lung adenocarcinomas specifically." (PMID 40940900, 2025). "BRAF mutations occur in approximately 2–4% of patients with lung adenocarcinoma and are mutually exclusive of EGFR, KRAS, and EML4–ALK." (PMID 39995841, 2025). "DDR1 is involved in the formation and progression of KRAS-mutant lung adenocarcinoma, particularly in early stages, and its upregulation acts as a compensatory mechanism in KRAS-knockdown cancer cells." (PMID 40563472, 2025). "In the Cancer Genome Atlas Lung Adenocarcinoma (TCGA LUAD) dataset, we found that, within KRAS-mutant tumors, those with STK11 mutations had higher PER1 mRNA expression (p = 0.0224) than those with wildtype LKB1." (PMID 40715535, 2025). "In lung adenocarcinoma, mutations of the EGFR or KRAS gene represent the most common oncogenic drivers." (PMID 40227775, 2025).
lung adenocarcinoma (continued). "The inactivation of the LKB1 gene has been confirmed in approximately 25% of KRAS-mutant lung adenocarcinomas (LUAD) and has emerged as a primary driver of immune-cold responses." (PMID 40429821, 2025). "KRAS is the most frequently mutated oncogene in NSCLC, with mutations present in 30% of lung adenocarcinomas and 5% of squamous cell carcinomas." (PMID 40558308, 2025). "A549 STK11/KRAS co-mutant lung adenocarcinoma cells are more sensitive to GLUT1 knockdown than other LUAD lines, however, they continue to proliferate." (PMID 40069402, 2025). "In conclusion, this retrospective analysis of the phase III JUNIPER trial identified the KL subtype as a candidate predictive biomarker for abemaciclib efficacy in platinum-refractory KRAS-mutant lung adenocarcinoma." (PMID 40231258, 2025). "Critical mutations in the RAS (rat sarcoma virus) oncogene superfamily, particularly the KRAS gene, play a pivotal role in lung adenocarcinoma initiation, progression, and tumor resistance." (PMID 40573310, 2025). "We demonstrate the application of Metient to lineage tracing data from a human KRAS-mutant lung adenocarcinoma cell line, tracking 100 clones in a mouse xenograft model." (PMID 39282311, 2025). "It is shown that SLC7A11 is overexpressed in patients with KRAS-mutant lung adenocarcinoma and has a positive correlation with tumor progression." (PMID 39569390, 2025). "Although we focus on KRAS-driven lung adenocarcinoma in this study, a flattening and even decrease in incidence in very old age is common to most cancer types." (PMID 41188600, 2025). "Recently, 3 different KRAS subtypes—KL, KP, and K—have been identified in lung adenocarcinoma based on gene expression and transcriptional profiling." (PMID 40231258, 2025). "Recent studies have further shown that SOX9 suppresses antitumor immunity in KRAS-driven lung adenocarcinoma, is correlated with immune-suppressive pathways across cancers, and promotes an immunosuppressive microenvironment in gastric cancer." (PMID 40692865, 2025). "These include basal-like breast cancer (BLBC), triple-negative breast cancer (TNBC), KRAS-dependent lung adenocarcinoma, osteosarcoma, and maxillary sinus squamous cell carcinoma." (PMID 40733189, 2025). "STK11/LKB1 inactivating mutations often cooccur with KRAS-activating mutations, and STK11/LKB1 inactivating mutations are also a driver of primary resistance to immunotherapy in KRAS-mutant lung adenocarcinoma (LUAD)." (PMID 40612109, 2025). "Profiling TIMP-1 in an array of lung adenocarcinoma cell lines, we found that the cell lines depicted as KRAS-independent appeared to express higher levels of TIMP-1 compared to cell lines that were KRAS-dependent." (PMID 41002380, 2025). "Our findings provided compelling evidence that CREPT depletion substantially attenuated proliferation and tumorigenesis in LUAD cells harboring KRAS or EGFR mutations, and impaired KRASG12D-induced lung adenocarcinoma formation in vivo." (PMID 40860160, 2025). "Here we identify the transcriptional repressor Capicua (CIC) as a key target inactivated by KRAS/MAPK signaling in lung adenocarcinoma." (PMID 41219537, 2025). "Overall, these findings clearly demonstrate that midostaurin, alone or in combination with decitabine, effectively disrupts cell-cycle progression and induces apoptosis in KRAS-driven lung adenocarcinoma organoids, highlighting their therapeutic potential." (PMID 40275403, 2025). "Similar findings have been reported in KRAS-driven lung adenocarcinoma and osteosarcoma, where LDHB is required for tumorigenesis, proliferation, and metastatic progression." (PMID 40733189, 2025). "In a mouse model of KRAS-driven lung adenocarcinoma, CD47 was identified as a key effector of KRAS-mediated immune suppression in the TME." (PMID 40333779, 2025).